APOE (apolipoprotein E)
Diseases named in the same sentence as APOE in open-access papers (continued):
Sharing a sentence is not in itself a finding about the gene and the disease.
cognitive decline (continued). "Four years later, follow-up data suggest that APOE *E4 is associated with poorer cognitive performance, as measured by the MMSE, and may influence the rate of cognitive decline in interaction with risk factors such as previous head injury or low education." (PMID 18620605, 2008). "Head injury was associated with greater decline in those with the APOE genotype when measured by the MMSE and fewer years of education were associated with greater cognitive decline for those homozygous or heterozygous for *E4 in association with the additional risk factor." (PMID 18620605, 2008). "Importantly, our results suggest that APOE-ε4 carriers with intact cognition may already exhibit early motor abnormalities, reinforcing the idea that motor deficits can precede overt cognitive decline." (PMID 41479611, 2025). "This APOE ε4 effect was confirmed in a recent study from the same cohort that included a larger sample size (675 mutation carriers and 594 controls), and further reported that the APOE ε2 genotype was associated with a delay in age-dependent cognitive decline as compared to non-carriers." (PMID 40275327, 2025). "Not all our patients who are APOE4 carriers, even those who are ApoE ε4/ε4 carriers, and not all our underweight patients show findings of CI, recalling that there are other risk factors for cognitive decline including age, cardiovascular disease risk factors, education level, and social engagement." (PMID 41439935, 2025). "Risk and protective factors of cognitive decline are complicated and multifaceted, including aging, living habits, nutrition, educational level, vascular pathology, sleep-disordered breathing, Apolipoprotein E (APOE) genotype, lack of Vitamin D, and earlier severe diseases." (PMID 40078638, 2025). "Interestingly, the APOE-ε4 carriership did not play a role in the risk of cognitive decline in the present analysis despite a trend for significance (p = 0.06)." (PMID 40263206, 2025). "The co-presence of APOE ε4 and APOC1 risk alleles has been reported to be more strongly associated with AD than APOE ε4 alone, indicating that the interaction between these two genes may contribute to the development of AD and cognitive decline." (PMID 40369256, 2025). "In APOEɛ4 carriers (i.e., individuals with at least one copy of the ɛ4 allele of the apolipoprotein E (APOE) gene, a well-established genetic risk factor for late-onset AD), higher dietary intake of α-tocopherol was significantly associated with a slower rate of cognitive decline." (PMID 40650110, 2025). "However, the synergistic effect between sleep disorder and APOE ε4 genotype on cognitive decline remains unclear." (PMID 38421124, 2024). "Furthermore, these authors also found that in individuals with at least one copy of the APOE ε4 allele, the rate of change in Aβ is not a significant predictor of cognitive decline." (PMID 38150745, 2024). "Given that there are modifiable health and lifestyle factors that may reduce cognitive decline and that APOE-specific interventions have been shown to be effective at mitigating cognitive decline in ɛ4 carriers, identifying these individuals at the earliest possible stage (i.e., SCD) is important." (PMID 38253819, 2024). "This may be because APOE ε4 status will play a primary role in predicting cognitive decline in individuals who carry an APOE ε4 allele, but when this allele is absent, Aβ becomes the primary predictor of cognitive decline." (PMID 38150745, 2024). "Nonetheless, the impact of APOE ε4 on cognition function in Aβ‐positive subjects has been displayed to vary widely between different cohorts, indicating that the Aβ‐independent effects of APOE ε4 on tau aggregation and cognitive decline are ambiguous and cohort‐dependent." (PMID 39014268, 2024). "However, our current study has revealed that ApoE ε4 allele and olfactory decline did not predict cognitive decline, indicating their limited clinical utility." (PMID 38660514, 2024).
cognitive decline (continued). "ApoE is involved in the transport of cholesterol and other lipids through the bloodstream and the CNS, and the ApoE4 isoform has been widely studied for its participation in neuroinflammation and cognitive decline in several neurological disorders, including alcohol abuse." (PMID 38295984, 2024). "Thus, further research interrogating differential markers of cytoarchitectural injury according to APOE across the preclinical to prodromal AD continuum may help to inform the probable etiology of nascent cognitive decline." (PMID 38212861, 2024). "Elevated CSF tau levels have been associated with decreased cortical plasticity and cognitive decline in APOE ε4, but not APOE ε3 carriers, supporting the notion that ApoE4 may enhance tau-mediated neurodegeneration." (PMID 36707869, 2023). "Given that elevated baseline CSF levels of soluble PDGFRβ (sPDGFRβ, a marker of injured pericytes) have been postulated to predict future cognitive decline in APOE ε4 carriers, we suppose that APOE could differentially modulate CBF and cognitive potentials in a pericyte-dependent manner." (PMID 37163446, 2023). "The interaction of APOE ε4 with the low‐density lipoprotein receptor‐related protein 1 could exacerbate the Aβ pathology, pointing toward a possible mechanism for the APOE ε4–induced cognitive decline." (PMID 38026513, 2023). "Although data confirming an association between diminished cognitive ability and depression are lacking, depression may be associated with ApoE status and hippocampal volume but not cognitive decline in aging adults with TBI." (PMID 38139244, 2023). "In contrast, greater WMH and lower BMI predicted faster hippocampal atrophy and cognitive decline in APOE-ε4 non-carriers, implying vascular risk factors play an important role in neurodegeneration and cognitive decline in non-demented elderly adults without APOE-ε4 allele." (PMID 35351867, 2022). "The mediation analyses between WMH-related neurodegeneration and cognitive decline in APOE-ε4 non-carriers showed that greater WMH partially explained the age-related hippocampal atrophy, which mediated the association between WMH and cognitive decline in APOE-ε4 non-carriers." (PMID 35351867, 2022). "This suggests that greater WMH may affect brain atrophy and cognitive decline independent of APOE-ε4 allele." (PMID 35351867, 2022). "This hypothesis is supported by our finding that the APOE locus was significantly associated with cognitive decline, but not with cognitive function at baseline." (PMID 36446774, 2022). "Fourth, cognitive status, which could modify the associations because APOE e4e4 carriers are more vulnerable to cognitive decline, was not evaluated." (PMID 36357490, 2022). "In addition, this was confirmed in a recent study that showed that APOE ε4 status was not statistically significant associated with cognition level, but was associated with cognitive decline." (PMID 36446774, 2022). "Finally, it has been shown that cognitive decline might be dependent on the ApoE-ε4 genotype and sex through FA metabolism and related metabolic pathways." (PMID 35389891, 2022). "Altogether, it is likely that older age-associated vascular diseases and underweight may contribute to faster neurodegeneration and cognitive decline in elderly adults without APOE-ε4 allele." (PMID 35351867, 2022). "Linear regression models were used to test the correlations between the AD-RAI and baseline cognitive measures, and linear mixed models with random intercepts and slopes were applied to investigate whether AD-RAI and APOE-ε4 can predict the level of cognitive decline." (PMID 35572149, 2022). "However, APOE but not CRP haplotype was associated with life-long cognitive decline in a longitudinal cohort, which does not support a causal effect of CRP on cognitive decline." (PMID 36348357, 2022).
cognitive decline (continued). "Hence, we supposed that CSF GAP-43 could be an early biomarker for cognitive decline and the effects of CSF GAP-43 on cognition may be correlated with APOE ε4 status and the number of ε4 alleles." (PMID 36611808, 2022). "However, it remains unclear how APOE-ε4 modulates the relationships between Aβ and WMH as well as their association with neurodegeneration and cognitive decline." (PMID 35351867, 2022). "The main effects of FBG are consistent with prior work that has found higher regional CBF, particularly in the MTL, in participants at risk for progression to AD (e.g., APOE ɛ4 carriers, those with subtle cognitive decline), but who are not yet considered cognitively impaired." (PMID 34415491, 2022). "Our study was one of only a few that reported significant interactions between leisure activities and APOE ε4 on cognitive decline, indicating that practicing leisure activities, particularly productive and social activities, might partly offset the risk of APOE ε4-related cognitive decline." (PMID 34616288, 2021). "APOE ε4 is associated with cognitive decline, but PRS is not." (PMID 34041846, 2021). "APOE ε4 was associated with cognitive decline risk, but PRS was not." (PMID 34041846, 2021). "However, a previous study conducted using UK Biobank data demonstrated that the association of device-measured PA with cognitive decline measures was not mediated by APOE." (PMID 34852818, 2021). "We hypothesized that there would be a significant statistical interaction where carriers of the APOE ε4 allele who engaged in leisure activities would have lower odds of cognitive decline compared to the noncarriers." (PMID 34616288, 2021). "Moreover, previous studies have revealed an association between the ApoE variant rs429358 (rather than rs7412) and cognitive decline in the aging population." (PMID 34135129, 2021). "Additionally, the APOE gene and SORL1 rs3737529 were associated with the rate of cognitive decline." (PMID 34214049, 2021). "We also had no information about the APOE genotype of participants, which could influence the association between metformin use and cognitive decline, as reported in previous studies." (PMID 34676236, 2021). "However, more work is needed to determine if APOE genotype may have a significant effect on the rate of cognitive decline in specific subsets of AD patients, such as within a given age group or gender or ancestry." (PMID 33148345, 2020). "Another possible reason is that as APOE2 can also protect against age-related cognitive decline independent of AD, cognitive decline could be a downstream event of APOE-associated pathways related to longevity independent of AD." (PMID 33074098, 2020). "Furthermore, in AD, some inflammatory proteins expressed in the brain, specifically α1-antichymotrypsin and apolipoprotein E (ApoE), especially ApoE4, clearly promote and, indeed, are necessary for amyloidogenesis that leads to cognitive decline in humans and/or animal models." (PMID 32704352, 2020). "The epigenetic changes in APOE accompanying AD‐related cognitive decline could result from the pathophysiology of the disorder or from adaptive responses of the organism as a result of AD, neither of which may be present at appreciable levels in the population studied here." (PMID 32346601, 2020). "Therefore lipid accumulation in the brain by diabetes or metabolic stress may boost the development of cognitive decline in people having ApoE ε4." (PMID 31675964, 2019). "For example, only the ApoE-4 allele on chromosome 19 is associated with cognitive decline over time, lowered onset age, and increased risk for late-onset sporadic AD in nondemented older adults, whereas ApoE-2 may confer protection." (PMID 31591322, 2019). "In addition, the Singapore Longitudinal Aging Study showed that the association of more leisure activities with a reduced risk of cognitive decline was stronger among carriers of the APOE ε4 allele than non-carriers." (PMID 31214016, 2019).
cognitive decline (continued). "APOE ɛ4 is also associated with altered levels of C-reactive protein, a systemic marker of inflammation which has been found to be associated with frailty, memory performance and lower medial temporal volume, and cognitive decline in a non-demented population." (PMID 31221191, 2019). "Therefore, the number of APOE ε4 risk alleles did not modify the association of either cholesterol intake or serum cholesterol levels with risk of global cognitive decline." (PMID 31888696, 2019). "Third, the APOE genotype may modify the association between BMI and cognitive decline; however, we could not investigate this association because more than half of the participants did not undergo APOE genotyping." (PMID 29719518, 2018). "Genetic variants in APOE and MAPT have time-dependent effects on cognition, which vary with disease stage: MAPT appears to have its greatest impact on cognitive decline in early PD, whereas APOE may have a more pronounced effect late in the course of the disease." (PMID 29692703, 2018). "Furthermore, diabetes leads to the disruption of the blood-brain barrier and decrease of apolipoprotein E (APOE) expression and the secretion of norepinephrine in the brain, involving the impairment of the glymphatic pathway and ultimately resulting in cognitive decline." (PMID 30429819, 2018). "APOE ε4 genotype and DM were negatively associated with cognitive decline regardless of age." (PMID 30126373, 2018). "However, APOE E4 allele possession did not moderate the relationships of depressive symptoms, neuroticism and allostatic load with cognitive ability and cognitive decline." (PMID 29451880, 2018). "The observed association between ApoE and cognitive decline may not be specific to PD and it could be observed in otherwise healthy older individuals." (PMID 30155299, 2018). "Given the roles that APOE e4 and CR1 AA/AG alleles have been reported to play in the deposition of β-amyloid, the breakdown of myelin and cognitive decline, the preponderance of these risk alleles may further suggest the presence of a survival effect among this cohort." (PMID 28344553, 2017). "In a study investigating the rate of cognitive decline post-stroke, and across carriers and non-carriers of apolipoprotein E ε4 (APoE ε4), findings indicate an association between the ApoE with declines in processing speed, the caveat being that speed was measured by the Coding task." (PMID 28983276, 2017). "While it is possible that Aβ related cognitive decline would be greater in APOE ε4 homozygotes compared to APOE ε4 heterozygotes, a test of this hypothesis would require the recruitment of very large samples of Aβ+ CN older adults and may therefore be better investigated using meta-analytic methods." (PMID 26430784, 2015). "Ultimately, these apoE-mediated differential effects on apoE receptors and Aβ accumulation could contribute to the mechanisms responsible for synaptic dysfunction and cognitive decline characteristic of observed in the EFAD mice that, ultimately, will translate to AD patients." (PMID 25871877, 2015). "In addition to increasing the risk for AD, APOE ε4 allele also accelerates cognitive decline in elderly non-demented individuals." (PMID 26574747, 2015). "Our results suggest that knowledge of the APOE genotype, while hardly precise in the prediction of AD, can play an important role in making recommendations to older adults regarding exercise as a means of maintaining brain integrity and preventing future cognitive decline and brain atrophy." (PMID 24795624, 2014). "Changes in BBB permeability, which could reflect functional alterations of pericytes and tight junction opening, have been recently suggested to precede neurodegeneration and cognitive decline during aging, as well as in apolipoprotein E (APOE) gene-manipulated mice." (PMID 24780507, 2014). "However, other studies did not detect an effect of the APOE ε4 allele on the rate of cognitive decline." (PMID 24914687, 2014).
cognitive decline (continued). "Therefore, MCI carriers of the APOE e4 allele seemed to be more atrophied and presented a faster cognitive decline compared to non-carriers." (PMID 25071554, 2014). "Thus, changes in BBB function do not seem to contribute to the increased risk of cognitive decline associated with certain ApoE genotypes." (PMID 24386372, 2013). "Furthermore, apoE ε4 promotes cognitive decline in middle-aged Down syndrome individuals." (PMID 22844635, 2012). "Therefore the ApoE genotype determines age-related changes in brain function that may reflect the increased vulnerability to cognitive decline in later life." (PMID 22558310, 2012). "Given that the domains of cognitive function that have demonstrated association with APOE genotype are similar to the early signs of LOAD and the timing of the onset of this cognitive decline, it has been suggested that ε4-related cognitive decline might be caused by preclinical LOAD." (PMID 21215387, 2011). "Since our previous analyses in the baseline assessment revealed significant APOE*BDNF interactions on cognitive performance, we also explored the presence of gene-gene interactive effects on cognitive decline in the longitudinal dataset." (PMID 41226628, 2025). "The observed differences in ERC-FC between APOE ε4 carriers and non-carriers may reflect early changes in functional brain organization associated with AD pathology, which may eventually lead to the cognitive decline observed in APOE ε4 carriers." (PMID 38867110, 2025). "Genetic factors also influence GAP-43 expression, with APOE ε4 carriers exhibiting higher CSF GAP-43 levels and a more rapid increase over time, indicating greater early synaptic vulnerability and cognitive decline acceleration." (PMID 40864734, 2025). "Our study points to potential biological pathways pertaining to specific domains within each APOE genotype group, and the findings suggest that immune-related pathways, plasma levels of polysaturated fatty acids, and bitter taste receptors may play roles in cognitive decline." (PMID 40725187, 2025). "It has been reported that SCD individuals carrying ApoE ε4 showed worse cognitive decline and more severe brain structural damage than those with SCD or ApoE ε4 alone." (PMID 41439935, 2025). "For example, a study highlights the involvement of APOE and its neighbouring genes (TOMM40, NECTIN2, BCAM) in AD and cognitive decline, partly reinforcing our findings of shared genetic susceptibility between vascular calcification and AD-related traits." (PMID 40149595, 2025). "Furthermore, although the APOE ε4 genotype was not directly associated with an increased risk of cognitive decline, it may contribute to telomere shortening." (PMID 40429722, 2025). "In AD, FABP7 expression is upregulated in astrocytes around amyloid plaques, while ApoE4 disrupts myelin homeostasis in the frontal cortex by altering ApoE and FABP7, contributing to early demyelination and cognitive decline." (PMID 41154661, 2025). "Our study points to potential biological pathways pertaining to specific domains within each APOE genotype group, and the findings suggest that immune-related pathways, plasma levels of polysaturated fatty acids, and bitter taste receptors may play some roles in cognitive decline." (PMID 40725187, 2025). "In the present study, ApoE−/− mice co-treated with an HFD and STZ exhibited hyperlipidemia, an increased atherogenic index, and cognitive decline." (PMID 40867851, 2025). "This review observed that both APOE positivity and SCD provide individual and multiplicative risks towards cognitive decline." (PMID 38253819, 2024). "Inclusion of lipid-trajectory and VIM groups improved risk-model predictive performance independent of APOE and AD or lipid-level PRSs, providing important real-world perspectives on how longitudinal levels and variation of blood-lipid concentrations contribute to risk of cognitive decline." (PMID 39586400, 2024).